U6 (U6 spliceosomal RNA )
Synonyms: LOC124903587
Gene: Small nuclear RNA gene on chromosome 15 (98,026,042 to 98,026,139, forward strand). Ensembl gene ENSG00000283372.
Gene Ontology:
Molecular function: U4 snRNA binding
Biological process: formation of quadruple SL/U4/U5/U6 snRNP; spliceosomal tri-snRNP complex assembly
Cellular component: U4/U6 x U5 tri-snRNP complex; U6 snRNP
Homologues: Orthologues: macaque U6 (95% identical), pig U6 (90% identical), dog U6 (63% identical). Paralogues in human: RNU6-1243P (85% identical), RNU6-1152P (84% identical), RNU6-41P (84% identical), RNU6-1048P (83% identical), RNU6-1060P (83% identical), RNU6-11P (83% identical), RNU6-15P (83% identical), RNU6-199P (83% identical), RNU6-19P (83% identical), RNU6-37P (83% identical), RNU6-44P (83% identical), RNU6-509P (83% identical), and 1288 more.